SNORD115-8 (small nucleolar RNA, C/D box 115-8)
Synonyms: HBII-52-8
Gene: Small nucleolar RNA gene on chromosome 15 (25,184,306 to 25,184,387, forward strand). Ensembl gene ENSG00000200726.
Gene Ontology:
Biological process: RNA processing
Cellular component: nucleolus
Homologues: Orthologues: chimpanzee SNORD115 (98% identical). Paralogues in human: SNORD115-38 (99% identical), SNORD115-6 (98% identical), SNORD115-11 (96% identical), SNORD115-29 (96% identical), SNORD115-34 (96% identical), SNORD115-36 (96% identical), SNORD115-42 (96% identical), SNORD115-43 (96% identical), SNORD115-10 (95% identical), SNORD115-12 (95% identical), SNORD115-15 (95% identical), SNORD115-16 (95% identical), and 37 more.